AGT (angiotensinogen)
Diseases named in the same sentence as AGT in open-access papers (continued):
Sharing a sentence is not in itself a finding about the gene and the disease.
Hypertension (continued). "Hypertension observed in offspring as a result of maternal high-fructose diet programming correlates with abnormal activation of the classic RAS axis, evidenced by increased levels of PRR, angiotensinogen, ACE, and AT1R in organs that regulate BP, such as the kidneys, blood vessels, and brain." (PMID 39911806, 2025). "Thus hypertension can be prevented in high estrogen states with alternative processing of angiotensinogen to Ang I rather than to Ang II." (PMID 39026347, 2024). "Although the source of macrophages contributing to pro-inflammatory cytokine elevation in the kidneys of Ang II-dependent hypertension has not been identified, production of IL-6, a stimulus of proximal tubular AGT expression, has been demonstrated in kidney-resident macrophages." (PMID 35887028, 2022). "Importantly, angiotensin I (AGT), and its endopeptidase neprilysin, MME, were also upregulated in these patients, suggesting hypertension in the uterine vascular circuits may also be contributing to the failure of blastocyst implantation." (PMID 32923410, 2020). "Interestingly, even though the kidney is not the main organ to produce angiotensinogen, increased production of angiotensinogen in the kidney became critical factor to induce the hypertension in model of type 2 diabetes mellitus." (PMID 31655853, 2020). "However, a recent meta-analysis was not able to show the association of the SNPs of ACE, AGT, and CYP11B2 genes and hypertension." (PMID 31511791, 2019). "Thus, intrarenal Ang II formation stimulated by the induction of AGT, renin and ACE may contribute to sodium and water retention and high blood pressure." (PMID 31680980, 2019). "Since angiotensinogen is the precursor molecule of angiotensins I and II that induce vasoconstriction and blood pressure increase, we may hypothesize that RREB1 may reflect the upregulation of a compensatory mechanism targeting to reduce hypertension." (PMID 29665821, 2018). "Evidence suggests that angiotensinogen is a more potent influencer of blood pressure than previously suspected, often more influential than other components of RAAS, and deserves more attention as a potential target in hypertension-related therapies, proposals that are supported by our findings." (PMID 26090382, 2015). "In addition, PEG-Bu could delivery AGT shRNA to efficiently inhibit the expression of AGT in BRL-3A cells, which was a key target for the treatment of hypertension." (PMID 23894329, 2013). "Therefore, PEG-Bu would be a promising non-viral vector for delivering AGT shRNA to BRL-3A cells for hypertension therapy." (PMID 23894329, 2013). "There are several candidate genes (ACE, angiotensinogen andaldosterone synthetase) in the RAAS that may potentially increase production ofeither angiotensin II or aldosterone, with suppression of renin, sodium retentionand hypertension." (PMID 17940670, 2007). "Thus, systemic and liver AGT is unlikely to contribute to sex disparities in hypertension." (PMID 28572913, 2017). "Furthermore, stimulation of AGT expression by estrogen may not explain previous findings that females exhibit resistance against hypertension and RAS-induced tissue injuries." (PMID 28572913, 2017). "Taken together, these observations indicate that oxidative stress-induced upregulation of AGT expression and downregulation of ACE-2 expression in RPTCs, resulting in higher angiotensin (Ang)II/Ang 1–7 ratio, may be key determinants of development of hypertension and nephropathy in diabetes." (PMID 26232095, 2015). "Our results suggested that urinary AGT/Cr may be a valuable biomarker for renal damage in ADPKD since intrarenal ischemic insults induced by cyst growth and subsequent intrarenal RAS activation may play a potential role in the development of hypertension and renal dysfunction in ADPKD." (PMID 26092580, 2015).
Hypertension (continued). "In addition to the elevated plasma levels of renin, angiotensin II, angiotensin-converting enzyme (ACE), angiotensinogen and aldosterone, renin receptors are also upregulated in patients with obesity compared with lean subjects, all of which may contribute to obesity-mediated hypertension." (PMID 40761303, 2025). "The results of our study have shown that oxidative stress parameters were not significantly dependent on the ACE and AGT gene genotypes in the group of COPD-only patients and the group of patients with comorbid COPD and hypertension." (PMID 32025262, 2019). "Accumulated visceral adipose tissue produce and secrete a number of adipocytokines, such as leptin, tumor necrosis factor-α (TNF-α), interleukin-6 (IL-6), angiotensinogen, and non-esterified fatty acids (NEFA), which induce development of hypertension." (PMID 18416854, 2008). "Importantly, the elevation of urinary AGT is also evident in patients with various pathologies, including hypertension and CKD, implying that renal Ang II levels increase even in individuals who do not exhibit elevated levels of circulating Ang II." (PMID 40131218, 2025). "Since the enzyme-linked immunosorbent assay (ELISA) system measuring AGT was developed, several clinical studies have demonstrated that urinary AGT excretion increases in patients with hypertension, CKD, or diabetes mellitus (DM) regardless of plasma AGT levels." (PMID 32410703, 2020). "However, urinary angiotensinogen was not augmented, although urinary protein is elevated in deoxycorticosterone acetate-treated rats, a model of RAAS-independent hypertension." (PMID 29600408, 2018).
cardiac hypertrophy (1,415 papers, 2005 to 2026). "Pellieux and colleagues have demonstrated that overexpression of angiotensinogen in the heart induced maladaptive cardiac hypertrophy, associated with reduction of PPARα and enzymes of fatty acid metabolism, while glucose oxidation was unchanged." (PMID 38397106, 2024). "The underlying mechanism is that adipose tissue synthesizes and secretes angiotensinogen, subsequently causing glomerular hypertrophy." (PMID 27733200, 2016). "Moreover, renal sinus fat accumulation is associated with glomerular hypertrophy and angiotensinogen produced in the renal tissue." (PMID 38558152, 2024). "Further mechanistic screening revealed that both interventions (hepatic AGT knockout vs systemic AngII inhibition) showed similar outcomes in terms of cardiac inflammation, myocardial fibrosis, and ventricular hypertrophy." (PMID 40888605, 2025). "This discrepancy implies the involvement of additional mechanisms beyond cardiac hypertrophy regulation in hepatic AGT‐mediated HFpEF pathology." (PMID 40888605, 2025). "SiRNA AGT monotherapy resulted in a moderate improvement in cardiac hypertrophy, similar to what occurred with captopril." (PMID 41156232, 2025). "Overexpression of AGT in the heart increases blood pressure and cardiac hypertrophy, and young spontaneously hypertensive rats show elevated tissue AGT expression." (PMID 39125667, 2024). "We previously showed cardiac hypertrophy in a pregnancy-associated hypertensive (PAH) mouse model, in which an increase in angiotensin II (Ang II) levels was induced by human renin and human angiotensinogen, depending on pregnancy conditions." (PMID 36736425, 2023). "The overexpression of the AGT gene in the heart increases BP and cardiac hypertrophy and young spontaneously hypertensive rats show an elevation of tissue AGT expression." (PMID 33925539, 2021). "Double-transgenic rats (dTGR) harboring the renin and angiotensinogen genes exhibit an HFpEF phenotype of diastolic dysfunction, preserved EF, systemic hypertension, cardiac hypertrophy, fibrosis, inflammation, and endothelial dysfunction, and dies between 7 and 8 weeks from severe heart failure." (PMID 35479330, 2022). "The CFs derived exosomes upregulated the expression of renin, angiotensinogen, AT1R, and AT2R while downregulated expression of angiotensin-converting enzyme 2 and increased production of Ang II in cultured cardiomyocytes thus overall exacerbated Ang II-induced cardiac hypertrophy." (PMID 34869682, 2021). "However, Efficacy of attenuating myocardial hypertrophy by pretreatment with SU6656 was more pronounced in AGT KO mice than in C57BL/6 mice." (PMID 24699426, 2014). "Considering the role of the serotonin and angiotensin systems in cardiac hypertrophy, we hypothesized that DNA variants in the 5-HT2A, 5-HTT, AGT, ACE, and AT1R genes could influence the risk for LVH." (PMID 20594303, 2010). "Double transgenic rats (dTGR) harbouring human renin and human angiotensinogen genes develop malignant hypertension, cardiac hypertrophy, renal damage, and endothelial dysfunction due to increased angiotensin II (Ang II) formation by the transfected human genes." (PMID 20721338, 2010). "Taken together, miR-133a targets a variety of pro-hypertrophic genes, namely SRF, cyclin D2, CTGF, RhoA, NFATc4, angiotensinogen, and AT1R, thus opposing cardiac hypertrophy." (PMID 33946230, 2021). "Renin converts angiotensinogen into angiotensin I, and angiotensin I is further metabolized to angiotensin II by ACE, finally affecting myocardial hypertrophy and fibrosis." (PMID 29892269, 2018). "Both hepatic AGT knockout and losartan‐mediated inhibition of the RAS effectively attenuated these structural changes, reducing heart weight, decreasing cardiomyocyte size, and ameliorating myocardial hypertrophy." (PMID 40888605, 2025).
cardiac hypertrophy (continued). "Tail vein injections of ASGP-coupled AGT ASO in male SHR from 10 to 20 weeks of age significantly inhibited cardiac hypertrophy and aortic medial hypertrophy, accompanied by reductions in cardiac AT1 receptor mRNA, hepatic AGT mRNA as well as plasma AGT and AngII concentrations." (PMID 30530571, 2019). "On the other hand, in transgenic mouse lines over-expressing angiotensinogen by the heart, Ang II is increased in cardiac muscle but not in plasma and ventricular hypertrophy was found despite no change in blood pressure." (PMID 24600438, 2014). "In hypertensive transgenic mouse lacking the synthesis of angiotensinogen, for instance, the local components of the RAS do not seem to be essential for the subsequent development of ventricular hypertrophy and fibrosis." (PMID 24600438, 2014).
endothelial dysfunction (570 papers, 2005 to 2026). In vascular diseases, endothelial dysfunction is a systemic pathological state of the endothelium (the inner lining of blood vessels) and can be broadly defined as an imbalance between vasodilating and vasoconstricting substances produced by (or acting on) the endothelium. "Visceral adipose tissue secretes bioactive molecules such as tumor necrosis factor-α (TNF-α), interleukin-6 (IL-6), and angiotensinogen, which collectively promote vascular inflammation, endothelial dysfunction, and increased arterial stiffness." (PMID 40703406, 2025). "We further demonstrated for the first time that RD treatment inhibited not only urinary NE elevation but also upregulation of AGT, oxidative stress, and endothelial dysfunction and subsequent BP elevation in the CIH condition." (PMID 30560943, 2018). "The AGT M235T polymorphism may contribute to IHD risk by increasing angiotensinogen levels, enhancing the renin-angiotensin-aldosterone system (RAAS), and promoting endothelial dysfunction and vascular remodeling." (PMID 40717713, 2025).
heart failure (551 papers, 2007 to 2026). Inability of the heart to pump blood at an adequate rate to meet tissue metabolic requirements. "While the renin‐angiotensin system (RAS) is implicated in heart failure pathogenesis, the causal contribution of angiotensinogen (AGT), the unique precursor of the RAS, to HFpEF remains undefined." (PMID 40888605, 2025). "Several cardiovascular diseases including myocardial infarction, coronary heart disease, heart failure, hypertrophy, etc. are associated with AGT polymorphism." (PMID 36557328, 2022). "A previous study showed that ELA prevented pressure overload-induced heart failure, possibly via the suppression of angiotensinogen (ACE) expression and pathogenic angiotensin II signaling, in mice." (PMID 33282918, 2020). "Polymorphic variants of angiotensinogen gene (M235T, rs699, and T174M, rs4762) could be associated with angiotensinogen levels, HT, left ventricular hypertrophy, and survival in heart failure." (PMID 32714484, 2020). "Since renin converts angiotensinogen into angiotensin I, it is likely that the children with heart failure also showed an increase in angiotensin I after administration of enalapril." (PMID 41155980, 2025). "In fact, they noticed that the T/T genotype of AGT M235T was more frequent in the heart failure group compared to the control (58% vs. 22%, p < 0.001)." (PMID 34834033, 2021). "To overcome this concern, we generated a heart failure animal model overexpressing human renin and human angiotensinogen by breeding CSQ‐tg mice with RA‐tg mice." (PMID 32056390, 2020). "IL6 stimulates angiotensinogen, serum amyloid P, fibrinogen, and orosomucoid-1 and inhibits transthyretin signifying men who developed heart failure had increased IL6 activity, whereas women with heart failure had decreased IL6 activity." (PMID 30132266, 2018). "Angiotensinogen levels are generally stable, but increase 2–3-fold during pregnancy, due to the fact that estradiol upregulates angiotensinogen expression, and decrease under conditions of severe renin upregulation, like in patients with heart failure treated with diuretics and RAS blockers." (PMID 39808369, 2025). "In vivo 18β‐glycyrrhetinic acid infusion may be a promising approach targeting hepatic AGT for heart failure with preserved ejection fraction (HFpEF) therapy." (PMID 40888605, 2025). "We developed a novel murine heart failure model (triple‐tg) by cross‐breeding calsequestrin transgenic mice with human renin and human angiotensinogen double‐transgenic mice and investigated the cardioprotective effect of imarikiren at clinically relevant doses." (PMID 32056390, 2020). "It would also be expected that AGT ASOs targeting liver-specific AGT synthesis may have improved efficacy and safety on other AngII-mediated diseases such as heart failure, an area ripe for future discovery." (PMID 30530571, 2019). "Animal models of heart failure demonstrate renal angiotensinogen mRNA expression consistent with RAAS activation in heart failure;38, 39, 40 the urine angiotensinogen level may likewise represent intrarenal RAAS activation, which could make it a useful biomarker in heart failure." (PMID 35620081, 2022). "The plasma angiotensinogen level reflects the systemic RAAS activity, which shapes human heart failure through multiple pathways." (PMID 35620081, 2022). "In this study, we generated human renin, human angiotensinogen, and canine calsequestrin transgenic (triple‐tg) mice, and then investigated the cardioprotective effect of TAK‐272 in this model in addition to its heart failure phenotypes." (PMID 32056390, 2020). "Although the PRA of WT or CSQ‐tg mice was comparable or slightly higher than that in healthy subjects and heart failure patients 19, 20, triple‐tg mice had much higher PRA due to overexpression of human renin and human angiotensinogen." (PMID 32056390, 2020).
heart failure (continued). "Angiotensinogen is processed to angiotensin II which increases TGF-β playing an important role in the pathophysiology of cardiac fibrosis, heart failure and glomerulosclerosis in humans." (PMID 26771187, 2016). "The urine angiotensinogen level is recognized as a marker of local intrarenal RAAS activation, which may be particularly important in heart failure and diuretic response given its proximity to the machinery of salt reabsorption." (PMID 35620081, 2022). "Renin, angiotensinogen, ACE, and Ang II receptors were all present in the heart, where they were found upregulated in models of cardiac injury, such as volume overload, myocardial infarction, and heart failure." (PMID 27652272, 2016).
COVID-19 (534 papers, 2020 to 2026). A disease caused by infection with severe acute respiratory syndrome coronavirus 2. "AGT is a hormone precursor involved in the blood pressure regulation cascade, and is implicated as a potential biomarker and linked to the severity of COVID-19." (PMID 35438176, 2022). "In this study, AGT levels were significantly increased in COVID-19 patients and were significantly correlated with ERC-BiP." (PMID 37849973, 2023). "AGT interacts with angiotensin converting enzyme 2 (ACE2), one of the main receptors responsible of SARS-CoV-2 entrance into the host cells which has been associated to COVID-19 cardiovascular complications." (PMID 35397534, 2022). "The AGT rs699 SNP is potentially valuable tool for predicting clinical COVID-19 outcomes." (PMID 35165525, 2022). "Importantly, we observed a strong correlation of AGT with markers of acute kidney injury (AKI; creatinine, urea), a frequent complication of COVID-19 and a risk factor for poor prognosis and fatal outcome." (PMID 34139154, 2021). "In our study ACE, REN, INS, KNG1, and AGT showed the highest connectivity within the complete ACE2 network and association with enriched diseases that are known to be a risk factor for a severe course of COVID-19." (PMID 33233425, 2020). "So far, no data of AGT polymorphism are available to explain its effects in COVID-19 patients." (PMID 34834033, 2021). "According to the cytoscape software, AGT is part of the RAS and bradykinin pathway in COVID-19, and in SARS-CoV fibrosis as well as lung injury in infected patients." (PMID 39594201, 2024). "We also observed higher levels of AGT and CLU in patients with COVID-19 admitted to the ICU compared to the other groups." (PMID 39027641, 2024). "Melatonin, angiotensinogen (AGT), CRP, and ceramide acid (Cer) levels were upregulated in COVID-19 patients (log2 (FC) = 0.486, 1.191, 2.002, and 1.712; P < 0.05)." (PMID 37849973, 2023). "Moreover, the negative correlation between sNRP-1 and angiotensinogen may indicate that enhanced RAS activation increases the risk of COVID-19." (PMID 34202613, 2021). "We compared the prevalence of ACE rs4646994, AGT rs699, and AGTR1 rs5186 polymorphisms between severe and non-severe cases of COVID-19." (PMID 34805533, 2021). "The validation study using MRM could specifically detect AGT, FGG, APOB, SERPING1, and SERPINA3 host peptides in COVID-19 severe patients." (PMID 33995121, 2021). "Here, we selected five significant proteins for COVID-19 non-severe versus severe comparison: heparin cofactor 2 (SERPIND1), thyroxine-binding globulin (SERPINA7), angiotensinogen (AGT), carbonic anhydrase-1 (CA1), and carbonic anhydrase-2 (CA2) for docking study." (PMID 33995121, 2021). "Proteins that decreased with COVID-19 in pregnancy but were increased in non-pregnant cases included vascular endothelial growth factor receptor 1 (VEGF-sR1 or sFLT-1) and angiotensinogen (AGT); yet, this could potentially be explained by their already elevated baseline among pregnant patients." (PMID 37016066, 2023).